DCD (dermcidin)
Description:
[DCD-1]: Found in sweat, has an antimicrobial activity during early bacterial colonization. The secreted peptide assembles into homohexameric complexes that can associate with and also insert into pathogen membranes. Once inserted in bacteria membranes forms anion channels probably altering the transmembrane potential essential for bacterial survival. Highly effective against E.coli, E.faecalis, S.aureus and C.albicans. Optimal pH and salt concentration resemble the conditions in sweat. Also exhibits proteolytic activity, cleaving on the C-terminal side of Arg and, to a lesser extent, Lys residues. [Survival-promoting peptide]: Promotes survival of neurons and displays phosphatase activity. It may bind IgG.
Synonyms: AIDD; DSEP; PIF; HCAP; DCD-1
Tractability: Antibody: UniProt places it where antibodies can reach, with high confidence; its Gene Ontology location is reachable by antibodies, with high confidence; UniProt predicts a signal peptide or a membrane-spanning region.
Target class: Enzyme; Hydrolase
Gene: Protein-coding gene on chromosome 12 (54,644,589 to 54,648,493, reverse strand). Ensembl gene ENSG00000161634.
Subcellular location: Secreted; Secreted (Survival-promoting peptide); Secreted (DCD-1); Membrane
Pathways (Reactome):
Immune System: Antimicrobial peptides
Gene Ontology:
Molecular function: lipid binding; monoatomic ion channel activity; protein binding; RNA binding; peptidase activity
Biological process: antibacterial innate immune response; antifungal innate immune response; defense response to bacterium; antimicrobial humoral immune response mediated by antimicrobial peptide; killing of cells of another organism; monoatomic ion transmembrane transport
Cellular component: extracellular exosome; extracellular region; membrane
Genetic constraint (gnomAD): Loss-of-function variants: 18 observed, 14.12 expected, observed/expected ratio (o/e) 1.27, 90% interval 0.88 to 1.81. The upper end of that interval is the gene's LOEUF score, 1.81, which puts it in group 6 of 6, group 1 being the genes least tolerant of losing a copy. Missense variants: 139 observed, 132.05 expected, observed/expected ratio (o/e) 1.05, 90% interval 0.92 to 1.21. Synonymous variants: 64 observed, 53.67 expected, observed/expected ratio (o/e) 1.19, 90% interval 0.97 to 1.47.
Homologues: Orthologues: chimpanzee DCD (91% identical). Paralogues in human: LACRT (26% identical).
Diseases named in the same sentence as DCD in open-access papers:
DCD is named in the same sentence as 62 diseases in open-access papers, as found by Europe PMC text mining. Sharing a sentence is not in itself a finding about the gene and the disease. The quoted sentences say what the papers report.
breast carcinoma (19 papers, 2006 to 2025). "DCD expression in breast tumors was associated with increased tumor size and presence of lymph node metastases, enhanced proliferation of 21NT breast cancer cell line, and migration of MCF-7 cells." (PMID 38417630, 2024). "A high expression of dermcidin was identified in approximately 10% of breast cancer patients and has been found to be closely associated with the advanced clinical stage and unfavorable clinical behavior due to regulation of tumor cell growth." (PMID 34198581, 2021). "Elevated levels of DCD are associated with the early progression of breast cancer and metastatic progression of melanoma." (PMID 32526853, 2020). "Dermcidin participates in the host defense against Staphylococcus aureus skin infection.Dermcidin expression is associated with breast cancer progression." (PMID 30271395, 2018). "To investigate the mechanisms underlying the growth and survival-promoting effects of DCD in MDA-MB-361 breast cancer cells, we analyzed the global gene expression profiles of control pLKO and DCD shRNA expressing cells." (PMID 25879571, 2015). "Using gain-of-function and loss-of-function approaches we confirmed that DCD acts as a growth and survival-promoting factor in breast cancer." (PMID 25879571, 2015). "DCD is linked to cell survival and breast cancer cell migration through Wnt signaling." (PMID 40029831, 2025). "High dermcidin expression is associated with tumor growth in gastric and breast cancer." (PMID 34198581, 2021). "Furthermore, we showed that DCD encodes for a secreted protein that binds to a candidate receptor present on the cell surface of breast cancer cells and neurons." (PMID 25879571, 2015). "Interestingly, dermcidin is also associated with tumor growth and tumor apoptosis in breast cancer." (PMID 34198581, 2021). "Recently, DCD has been shown to be expressed in breast cancer cells, hepatocytes, and human placental tissues (56, –, 58)." (PMID 40422282, 2025). "We have done a study to evaluate the role of Dermcidin (DCD) in breast cancer tumorigenesis using as model MDA-MB-361, a breast carcinoma cell line widely used to investigate breast cancer pathobiology." (PMID 27746730, 2016). "Correlating with this, MDA-MB-361 breast cancer cells expressing DCD shRNA displayed a more differentiated luminal epithelial cell phenotype compared to control cells." (PMID 25879571, 2015). "Here, we describe for the first time the co-expression of DCD and DCD-SV in normal skin tissue and breast cancer cell lines using validated and novel specific antibodies against different portions of these proteins." (PMID 25879571, 2015). "To investigate the role of DCD in breast tumorigenesis, we analyzed the consequences of its downregulation in human breast cancer cell lines using three specific shRNA lentiviral vectors." (PMID 25879571, 2015). "Proteolysis-inducing factor, a cachexia-inducing tumour product, is an N-glycosylated peptide with homology to the unglycosylated neuronal survival peptide Y-P30 and a predicted product of the dermcidin gene, a pro-survival oncogene in breast cancer." (PMID 16685272, 2006). "Demonstration of altered expression in hepatic tumours would confirm the potential of dermcidin to act as an oncogene in tumours other than breast cancer." (PMID 16685272, 2006). "Dermcidin has been identified as a candidate oncogene in breast cancer and stable transfection has been shown to stimulate cell growth and inhibit menadione-induced cell death, as assessed by cell counting." (PMID 16685272, 2006). "While DCD expression is associated with disease progression and survival in breast cancer patients, its role after irradiation treatment is not well understood." (PMID 40029831, 2025). "Notably, Dermcidin (DCD) and prolactin inducible protein (PIP) serve as biomarkers, with DCD linked to breast cancer and lymph nodes, while PIP is overexpressed in breast and prostate cancer." (PMID 40305328, 2025).
breast carcinoma (continued). "Psoriasin and dermcidin (DCD) have been previously indicated as markers for breast cancer 26,27." (PMID 36725900, 2023). "DCD is a neural growth and survival factor and its therapeutic inhibition may be an effective treatment in a subset of breast carcinomas." (PMID 26949398, 2016). "To assess the function of DCD in breast cancer cells with high endogenous expression, we generated derivatives of the MDA-MB-361 human breast cancer cell line expressing three different shRNAs against DCD (IBC-I, IBC-II, and IBC-III) using pLKO plasmid-derived lentiviruses." (PMID 25879571, 2015). "In breast cancer, a proteomic approach identified cell surface GRP78 and Dermcidin (DCD) as cooperative regulators of breast cancer cell migration through Wnt signaling." (PMID 37605113, 2023). "In breast cancer, cell surface GRP78 and dermcidin cooperate to regulate breast cancer cell migration via Wnt signalling." (PMID 36224652, 2022). "A recent study demonstrated that Dermcidin (DCD) acts as a novel binding partner of csGRP78 in breast cancer cells, and that DCD enhanced breast cancer cell migration." (PMID 35625836, 2022). "As regards the mechanisms, dermcidin has been found to modulate the HER-2-mediated signal pathway, which is one of the major pathways in breast cancer." (PMID 34198581, 2021).
melanoma (12 papers, 1999 to 2025). A malignant, usually aggressive tumor composed of atypical, neoplastic melanocytes. "Further studies have shown that high dermcidin levels are associated with late-stage melanoma in patients with metastasis, indicating a role in melanoma progression and suggesting a prognostic value as a marker." (PMID 34885944, 2021). "Among cutaneous malignancies, having high serum levels of dermcidin at the moment of melanoma diagnosis has been associated with the metastatic progression of melanoma among melanoma patients." (PMID 34198581, 2021). "We previously demonstrated that in stage II melanoma patients, serum levels of dermcidin (DCD) were associated with metastatic progression." (PMID 32485045, 2020). "Furthermore, the presence of DCD expression was less likely associated with SSM melanoma subtype (P = 0.033)." (PMID 34757537, 2022). "However, an analysis based on classification together with multivariate statistics showed that tumor stage, vitronectin and dermcidin levels were associated with the metastatic progression of patients with early‐stage melanoma." (PMID 27216146, 2016). "Serum dermcidin, an antibiotic peptide secreted by sweat glands, is elevated in patients with early-stage melanoma with respect to healthy subjects." (PMID 39028721, 2024). "The new synthetic analogues were more water-soluble, maintained or improved the cytotoxicity and selectivity for melanoma cells, and preserved the molecular target (dermcidin protein), allowing for further investigations with these analogues in vivo." (PMID 35621952, 2022). "Isolated from the marine bacteria Serinicoccus sp., seriniquinone (SQ1) has been characterized by its selective activity in melanoma cell lines marked by its modulation of human dermcidin and induction of autophagy and apoptosis." (PMID 34885944, 2021). "To analyze the prognostic value of these proteins, we compared serum cytokine and DCD levels of early‐stage melanoma patients that remained disease‐free at the end of the follow‐up period, with those obtained from early‐stage patients who developed metastasis." (PMID 32485045, 2020). "Although melanoma patients have increased serum dermcidin levels, the REPTree classifier showed that levels of dermcidin <2.98 μg/ml predict metastasis in AJCC stage II patients." (PMID 27216146, 2016). "The presence of DCD expression was less likely associated with superficial spreading melanoma subtype but significantly associated with non-progressive disease." (PMID 34757537, 2022). "Consequently, this compound emerged as both a potential treatment for melanoma and a tool to help in elucidating the role of dermcidin in this type of cancer." (PMID 35621952, 2022). "Furthermore, these data clearly pointed to the cytokines IL‐4, GM‐CSF, and DCD as the most powerful biomarkers in predicting melanoma metastasis in conjunction with the Breslow thickness." (PMID 32485045, 2020). "In sum, cytokines and DCD alone represent a weak source of melanoma prognosis." (PMID 32485045, 2020). "DCD serum levels are elevated in melanoma patients with respect to the healthy controls, although in the early‐stage patients who develop metastasis during follow‐up there is a significant decrease in DCD levels." (PMID 27216146, 2016). "Five proteins were selected for validation as prognostic factors in 348 melanoma patients and 100 controls by ELISA: serum amyloid A and clusterin; immune system proteins; the cell adhesion molecules plakoglobin and vitronectin and the antimicrobial protein dermcidin." (PMID 27216146, 2016). "Increased levels of IL-4, along with GM-CSF and dermcidin (DCD), have been recognized as significant biomarkers in early-stage melanoma." (PMID 40636453, 2025). "Previous studies have shown that SQ1 and its analogues modulated DCD mRNA expression in HCT-116 (colorectal carcinoma), PC-3M (prostate carcinoma), MALME-3M (melanoma) and SK-MEL-28 (melanoma) cell lines." (PMID 34885944, 2021).
melanoma (continued). "It has previously been reported that the expression of dermcidin was not identified in epithelial tumors, melanoma, and extramammary Paget’s disease." (PMID 34198581, 2021).
Hyperglycemia (6 papers, 2012 to 2024). An increased concentration of glucose in the blood. "We reported from our laboratory that dermcidin-induced hyperglycemia was due to the impairment of NO which causes endothelial dysfunction relating to the elevated HbA1c." (PMID 31300527, 2019). "We also report herein the neutralization of the dermcidin-induced atherosclerotic risk by insulin and by aspirin via the synthesis of NO through the control of both hyperglycemia and hypertension." (PMID 24649391, 2014). "It was also reported before that the hyperglycemia in T1BDM in humans developed due to the presence of dermcidin could be controlled by stimulating the systemic NO synthesis without using external insulin administration." (PMID 24711743, 2014).
hepatocellular carcinoma (5 papers, 2006 to 2022). A malignant tumor that arises from hepatocytes. "Serum dermcidin levels were significantly increased in hepatocellular carcinoma patients and were positively correlated with metastasis." (PMID 34198581, 2021). "Preliminary results suggest that certain hepatic carcinoma cell lines express dermcidin, and the development of siRNAs will facilitate investigation of the effects of inhibiting expression in these cells and in overexpressing HuH7s." (PMID 16685272, 2006). "We have previously documented that dermcidin (DCD) acts as a survival factor in prostate cancer cells exposed to either hypoxia or oxidative stress, and hepatoma cell lines subject to oxidative stress." (PMID 18594538, 2008).
pancreatic cancer (5 papers, 2008 to 2022). "Reduced levels of dermcidin-derived peptides has been detected in the sweat of patients with atopic dermatitis in association with an impaired cutaneous antimicrobial defense, while the increased expression of dermcidin has been demonstrated in lung, prostate and pancreatic cancer cells." (PMID 35884778, 2022). "The increased expression of dermcidin has been demonstrated in lung, prostate and pancreatic cancer cells suggesting its role in proliferative pathological changes." (PMID 34358033, 2021). "Both pancreatic cancer cell lines used in this study demonstrated DCD mRNA expression." (PMID 18594538, 2008). "It was these findings that stimulated the hypothesis for the present study, that is, that DCD mRNA would be upregulated by the induction of oxidative stress in prostatic and pancreatic cancer cell lines." (PMID 18594538, 2008). "However, three (60%) of the pancreatic cancer samples and the single cholangiocarcinoma specimen had moderate/high levels of dermcidin expression." (PMID 18594538, 2008). "As such, further studies of DCD expression in human pancreatic cancer and the relationship with patient phenotype and outcome may be the optimum way of taking the biology of human DCD forward." (PMID 18594538, 2008). "In contrast, 60% of primary pancreatic cancer samples expressed significant quantities of DCD mRNA." (PMID 18594538, 2008). "Dermcidin expression was assessed in prostatic and pancreatic cancer cell lines, with and without induction of hypoxia or oxidative stress." (PMID 18594538, 2008). "Of the two pancreatic cancer cell lines, one expressed dermcidin moderately but neither showed a response to hypoxia or oxidative stress." (PMID 18594538, 2008). "However, dermcidin expression by prostatic or pancreatic cancer cell lines was not substantially increased by induction of hypoxia or oxidative stress." (PMID 18594538, 2008).
acne (4 papers, 2020 to 2024). An inflammatory process of the sebaceous glands which is characterized by comedones, nodules, papules and/or pustules on the skin. "Dermcidin has been identified as a biomarker for Alzheimer’s disease (AD), asthma, acne vulgaris, severe obstructive sleep apnea, and facioscapulohumeral muscular dystrophy." (PMID 34198581, 2021). "Dermcidin is an antimicrobial peptide and manifests as anti-inflammatory properties in acne vulgaris; isotretinoin can ameliorate acne vulgaris via enhancing Dermcidin level." (PMID 32685503, 2020). "Nonetheless, several AMPs share specific amino acid motifs with human endogenous AMPs, including hBDs, LL-37, dermcidin, RNAse 7, or granulysin, which may explain their anti-acne properties." (PMID 39744637, 2024). "Dermcidin is also found in lower concentrations in plasma as well as in the lesional skin of acne patients when compared to controls, and increases upon treatment with low or conventionally dosed isotretinoin, a retinoid which has been used with varied success for the treatment of HS." (PMID 34696185, 2021). "While dermcidin, granulysin (GNLY), RANTES (CCL5), perforin, CXCL9, and two neuropeptides (substance P and chromogranin B) remained unaffected either in untreated acne patients as well as by isotretinoin treatment." (PMID 39744637, 2024).
Hypertension (4 papers, 2012 to 2025). The presence of chronic increased pressure in the systemic arterial system. "The effect of dermcidin isoform 2 (dermcidin), an environmentally induced stress protein, was investigated on the genesis of diabetes mellitus and hypertension, the two major atherosclerotic risk factors." (PMID 24649391, 2014). "As diabetes and hypertension are the two major risk factors for AIHD, the possible role of dermcidin as an aggregating agent was studied." (PMID 24649391, 2014). "Aspirin was found to reduce hypertension by reduction of plasma dermcidin level, neutralized the effect of cyclooxygenase, and restored the pancreatic insulin synthesis through NO synthesis." (PMID 22448321, 2012). "In this sense, dermcidin, a protein produced due to stress, was unique in its role in the development of hypertension." (PMID 22448321, 2012). "We have also reported that dermcidin was not only a diabetogenic protein for T1BDM but also had a critically important role in the development of arterial hypertension through the inhibition of the synthesis of (r)-cortexin in the kidney cortex cells due to the inhibition of NO synthesis." (PMID 24649391, 2014). "And, as such, the dermcidin-induced reduction of plasma NO level could be suggested to result in the increase of systemic hypertension." (PMID 22448321, 2012). "Dermcidin was a potent inhibitor of insulin activated nitric oxide synthase and thereby might play a critical role in the development of hypertension." (PMID 22448321, 2012). "Furthermore, dermcidin was found to be capable of inducing essential hypertension in man." (PMID 25324696, 2014). "As dermcidin was capable of inhibiting insulin synthesis and as the lack of insulin synthesis was found to lead to increased dermcidin synthesis, a vicious circle would be implicated to worsen both T1BDM and hypertension due to the lack of systemic insulin synthesis." (PMID 24649391, 2014).
lung carcinoma (4 papers, 2020 to 2024). "Dermcidin has also recently been proposed as a prognostic biomarker of lung cancer together with S100-A9." (PMID 33396627, 2020). "Analysis of exhaled breath condensate with LC-MS/MS revealed that dermcidin expression was statistically higher in lung cancer versus healthy volunteers, implying that this non-invasive sampling may serve as biomarkers for lung cancer diagnosis or prognosis." (PMID 39028721, 2024). "Dermcidin expression is higher in lung cancer patients compared with that in healthy subjects." (PMID 34198581, 2021).